DENND2A (DENN domain containing 2A)
Description:
Guanine nucleotide exchange factor (GEF) which may activate RAB9A and RAB9B. Promotes the exchange of GDP to GTP, converting inactive GDP-bound Rab proteins into their active GTP-bound form. May play a role in late endosomes back to trans-Golgi network/TGN transport.
Synonyms: KIAA1277; FAM31D
Tractability: No criterion of Open Targets' tractability assessment is met for any kind of drug.
Gene: Protein-coding gene on chromosome 7 (140,518,418 to 140,673,993, reverse strand). Ensembl gene ENSG00000146966.
Subcellular location: Cytoplasm, cytoskeleton
Pathways (Reactome):
Vesicle-mediated transport: RAB GEFs exchange GTP for GDP on RABs
Gene Ontology:
Molecular function: guanyl-nucleotide exchange factor activity
Biological process: retrograde transport, endosome to Golgi
Cellular component: actin cytoskeleton; cytosol; cytoskeleton
Genetic constraint (gnomAD): Loss-of-function variants: 51 observed, 101.89 expected, observed/expected ratio (o/e) 0.5, 90% interval 0.4 to 0.63. The upper end of that interval is the gene's LOEUF score, 0.63, which puts it in group 2 of 6, group 1 being the genes least tolerant of losing a copy. Missense variants: 1,134 observed, 1,318.4 expected, observed/expected ratio (o/e) 0.86, 90% interval 0.82 to 0.9. Synonymous variants: 520 observed, 522.34 expected, observed/expected ratio (o/e) 1, 90% interval 0.93 to 1.07.
Homologues: Orthologues: chimpanzee DENND2A (99% identical), macaque DENND2A (96% identical), dog DENND2A (88% identical), pig DENND2A (87% identical), rat Dennd2a (83% identical), mouse Dennd2a (82% identical), rabbit DENND2A (82% identical), guinea pig DENND2A (68% identical), tropical clawed frog dennd2a (65% identical). Paralogues in human: DENND2B (49% identical), DENND2C (44% identical), DENND2D (21% identical).
Diseases named in the same sentence as DENND2A in open-access papers:
DENND2A is named in the same sentence as 12 diseases in open-access papers, as found by Europe PMC text mining. Sharing a sentence is not in itself a finding about the gene and the disease. The quoted sentences say what the papers report.
chronic hepatitis B (1 paper, 2024). "In conclusion, our research highlights DENND2A and SASH1 in the immune system during HBV infection and 10M-DEN3SN as the potentially effective drug in the treatment of chronic hepatitis B." (PMID 38240571, 2024).
glioma (1 paper, 2020). A benign or malignant brain and spinal cord tumor that arises from glial cells (astrocytes, oligodendrocytes, ependymal cells). "Recently, hypoxia-activated circ-DENND2A was revealed to promote the migratory and invasive capacities of glioma cells through competitively binding to miR-625-5p." (PMID 31937318, 2020).
ischemic stroke (1 paper, 2020). A stroke disorder caused by obstruction of blood flow to the brain, due to thrombotic (local blood clot formation) or embolic (due to a blood clot or other material traveling from another site) event. "Previous studies indicated that DENND2A was related to ischemic stroke and Parkinson’s disease." (PMID 33033491, 2020).
lung adenocarcinoma (1 paper, 2020). A carcinoma that arises from the lung and is characterized by the presence of malignant glandular epithelial cells. "We found that DENND2A was significantly suppressed in lung adenocarcinoma (LUAD) and lung squamous cell carcinoma (LUSC) samples compared with normal tissues." (PMID 33033491, 2020).
Obesity (1 paper, 2025). Accumulation of substantial excess body fat. "PMAIP1 has been reported to be associated with obesity, body mass index (BMI), and height in humans and average daily gain (ADG) in pigs, while DENND2A has been proposed as a candidate gene for BFT." (PMID 39932890, 2025).
tumor (4 papers, 2018 to 2024). "On the other hand, DENND2A is known as GEF in the Rab family, and SASH1 is reported in tumor suppression, cellular proliferation, and adhesion (35, –, 37)." (PMID 38240571, 2024).
cancer (1 paper, 2020). A tumor composed of atypical neoplastic, often pleomorphic cells that invade other tissues. "Nevertheless, the function of DENND2A in cancers remained elusive." (PMID 33033491, 2020).
heart disease (1 paper, 2019). "Although the function of DENND2A has rarely been reported to be relevant to diseases, Rab9-dependent mitophagy has been shown to contribute to heart disease." (PMID 30984102, 2019).
infection (1 paper, 2020). The state of being infected such as from the introduction of a foreign agent such as serum, vaccine, antigenic substance or organism. "Similarly, observed downregulation Rab9a GEF-encoding genes, DENND2a and DENND2b, in the E phase of infection does not correlate with the increase of Rab9a membrane-associated pool within the inner PrAC." (PMID 33042998, 2020).
DENND2A also shares sentences with these, for which no sentence is quoted: Hepatitis (1 paper); lung squamous cell carcinoma (1); Parkinson disease (1).